CTTN (cortactin)
Diseases named in the same sentence as CTTN in open-access papers (continued):
Sharing a sentence is not in itself a finding about the gene and the disease.
tumor (continued). "However, when the samples were tested for phosphorylated CORTACTIN, we found increased levels of phospho-CORTACTIN in tumor cells exposed to factors released by the “primed” neutrophils." (PMID 23423155, 2013). "Indeed, PP2 inhibitors display similar effects as observed after treatment of tumour cell lines with the experimental drugs Si135 and Si162, including inhibition of c-Src, followed by a reduced activation of cortactin and paxillin." (PMID 21152443, 2010). "Finally, SH3 and multiple ankyrin repeat domains 2 (SHANK2), which binds the SH3 domain of cortactin and is thereby thought to promote cell motility at growth cones of neurons, is 51-fold up-regulated in the tumor." (PMID 20174472, 2010). "CTTN mainly participates in cytoskeletal regulation and plays a pivotal role in tumor metastasis." (PMID 19835603, 2009). "Tumours that overexpress cortactin were largely positive for EGFR." (PMID 18268492, 2008). "Thus, the functional properties of cortactin, together with amplification of chromosome locus 11q13, suggest a link between its overexpression and tumour invasion and/or metastasis." (PMID 18268492, 2008). "In the present study of 176 tumours, we found by quantitative immunohistochemical analysis of TMAs, that cortactin expression status in the tumours of patients with HNSCC is a strong independent prognostic factor for local recurrence as well as disease-free and overall survival." (PMID 18268492, 2008). "In all, 77 out of 176 tumours were designated as cortactin overexpressors." (PMID 18268492, 2008). "Of the HNSCC tumours that met inclusion criteria, all were interpretable for cortactin staining." (PMID 18268492, 2008). "Deregulation of these processes by overexpression of cortactin might mediate the migratory and invasive potential of tumor cells." (PMID 16536875, 2006). "The role of cortactin overexpression on MG tumor development in vivo, either in the absence or presence of co-expression of cyclin D1, was studied in a cohort of 100 multiparous mice that underwent multiple pregnancies/lactations to force transgene expression in the MG." (PMID 16536875, 2006). "Overexpression of cortactin could contribute to the emergence of invasive tumor phenotypes in a variety of ways, including enhanced actin polymerization, down-regulated epidermal growth factor receptor, and molecule interactions between cyclin D1 and CD44 proteins." (PMID 38077360, 2023). "Therefore, we speculated that Rac1 combined with CTTN might affect the invasive and migratory abilities of tumor cells by altering the cytoskeleton." (PMID 37970440, 2023). "In addition, studies have confirmed that cortactin is highly expressed in many tumours." (PMID 33191645, 2021). "Moreover, Src-mediated phosphorylation of CTTN can promote tumor cell migration in HCC." (PMID 32120844, 2020). "Therefore, this study confirms that UCHL1 occupies a tumor suppressor role in NPC metastasis by mediating CTTN degradation, and may represent a novel therapeutic target for NPC treatment." (PMID 32120844, 2020). "Therefore, we also investigated whether peptide C16 would influence distribution and phosphorylation of cortactin in tumor cells." (PMID 27323814, 2016). "Based on the findings that: (i) CORTACTIN is an important regulator of cellular migration and (ii) neutrophils enhance the migration of HNC cells, we hypothesized that neutrophils “exploit” high tumoral CORTACTIN levels to promote the migration of the tumor cells." (PMID 23423155, 2013). "ERK1/2 phosphorylation of cortactin has emerged as an important positive regulatory modification, enabling cortactin to bind and activate the Arp2/3 regulator neuronal Wiskott-Aldrich syndrome protein (N-WASp), promoting actin polymerization and enhancing tumor cell movement." (PMID 21079800, 2010). "However, we identified a subset of 29 tumours in which cortactin and EGFR overexpression could be uncoupled." (PMID 18268492, 2008).
tumor (continued). "The potential for tumor invasiveness was assessed based on the immunoexpression of the following invadopodia-forming proteins: MT1-MMP, cortactin, Tks-4 and Tks5." (PMID 39941035, 2025). "Studies show that the proteins Tks-4, Tks-5, cortactin, and MT1-MMP are closely related to the tumor invasion process." (PMID 39941035, 2025). "The function assay suggested the CTTN gene’s role in cell proliferation and invasion through the EMT pathway and highlighted the importance of the TCA cycle’s importance in tumor immunity." (PMID 39451768, 2024). "Consistently, the confusion matrix statistics showed that the normal and tumor samples can be reliably separated using gene expression data for CD2AP, GRB2, WASL, SRC, CTTN, CAPZA1, and Tks4 with 97% sensitivity and 80% specificity." (PMID 39234565, 2024). "Invadopodia, characterized by co-localization of cortactin and F-actin, and high MMP14 expression in invadopodia are essential for tumor cell invasion." (PMID 37686118, 2023). "Actin rearrangement changes the original cell morphology and adhesion ability, which is a necessary condition for tumor invasion and metastasis, and MMP14, as well as cortactin, plays a key role in the formation of invadopodia." (PMID 37686118, 2023). "To further study the CTTN protein expression, we performed immunohistochemistry staining of 42 ESCC tumor samples and 10 normal esophageal samples." (PMID 35121801, 2022). "Then, we analyzed the histoscores of Hsp70, Hif1α, cortactin MMP14, and MMP2 in both tumor and normal tissues and observed significantly higher expression levels of these proteins in OSCC tissues." (PMID 35957827, 2022). "In CRC, miR-542-3p can impede tumor promotion via TUG1, and inhibit the proliferation, migration, and invasion through OTUB1, cortactin, or PI3K/AKT signaling." (PMID 35427373, 2022). "The overexpression of CTTN, CLDN-1, and CLDN-4 genes was correlated positively with the extent of tumor size." (PMID 33407452, 2021). "The Abl family of non-receptor tyrosine kinase (Arg) also mediates epidermal growth factor (EGF)-induced cortactin phosphorylation, triggering actin polymerization in invadopodia, ECM degradation, and tumor cell invasion." (PMID 32104508, 2020). "Cell movement mediated by cortactin induces the epithelial–mesenchymal transition (EMT) and then participates in relevant disease processes, such as tumor proliferation, migration, and invasion." (PMID 33195233, 2020). "Immunohistochemically, we observed higher cortactin expression and Tyr421-phosphorylation in PDAC metastases compared to primary tumor tissues." (PMID 30976201, 2019). "Circulating tumor cells adhering on the endothelial layer extend protrusions, which are rich in invadopodia markers MMP14, cortactin, Tks4, and Tks5." (PMID 31167468, 2019). "In our cohort of tumor specimens from patients with histologically confirmed PDAC, we observed a significant upregulation of cortactin and phosphorylated (i.e. activated) cortactin in metastases of PDAC patients as compared to primary tumors." (PMID 30976201, 2019). "Src/FAK/p-cortactin, Akt/mTOR/c-Myc, UBE2S/hypoxia, and reactive oxygen species (ROS) signaling activated and promoted the metastasis of A431-III tumor cells." (PMID 31731716, 2019). "Co-localization of Arg, cortactin, and fluorescently activated MMP Sense was observed in primary tumor sections, supporting enrichment of Arg in matrix-degrading tumor cell protrusions." (PMID 29774130, 2018). "The results again demonstrated an increase in cortactin and Arp3 protein levels in MCC tumor samples compared to the control." (PMID 29093086, 2018). "CTTN and PBF expression in matched tumor/normal samples (n = 59) confirmed a strong correlation pattern (P = 2.74×10−6; rs = 0.564)." (PMID 27603901, 2016). "In a series of matched tumor and normal DTC specimens, CTTN mRNA showed a significant 1.5-fold induction in tumors compared with matched normal thyroid (P < .05; n = 43)." (PMID 27603901, 2016).
tumor (continued). "To clarify how invadopodia formation in tumor cell lines evolves during C16 treatment, we utilized time-lapse confocal imaging using GFP-cortactin-transfected cells cultured on fluorescent gelatin." (PMID 27323814, 2016). "As PBF and CTTN are induced in multiple tumor types, our study now identifies PBF as an undercharacterized target to block tumor cell movement." (PMID 27603901, 2016). "We also showed that a key mediator of cell motility and metastasis, cortactin, was significantly inhibited by CBF in HCT116 cell line and in xenografts HCT116 tumours." (PMID 26134506, 2015). "Another possible explanation is the common function of the simultaneously amplified genes of 11q13 (CTTN, FADD, CCND1, and FGF4) in tumor growth and invasion." (PMID 26194878, 2015). "In conclusion, CBF possess the unique capacity to inhibit the overexpression of cortactin in HCT116 cells and nude mouse models bearing HCT116 tumours." (PMID 26134506, 2015). "Stimulation of tumor cells with EGF leads to phosphorylation of serine residues 405 and 418, coincident with a characteristic shift in cortactin electrophoretic mobility from 80 to 85 kDa in SDS-PAGE." (PMID 24971065, 2014). "Thus, increased expression of cortactin might promote tumor cell invasion and metastasis." (PMID 16536875, 2006). "Lastly, presence of extra-cellular matrix proteins, abundantly seen in the tumour micro-environment of PDAC, could also enhance cellular process co-localisation of AHNAK2 with Cortactin." (PMID 39849106, 2025). "However, less is known about the expression patterns of CTTN and other genes related to it or invadopodia formation in OSCC during tumor progression in particular." (PMID 37623256, 2023). "In both groups (Fra-2 cl 1 and cl 2), some interesting genes could be identified, e.g., in the Fra-2 cl 1 primary tumours LGALS1, ADRM1, and CTTN, which were upregulated and LUM (Lumican), MAN1A1, and SPARC, which were significantly downregulated." (PMID 34693476, 2022). "Differential expression of CTTN and of YKT6 has been related to cell migration and tumor invasion." (PMID 36016316, 2022). "In addition, among our top 50 dysregulated phosphoproteins were cortactin and tight-junction protein-family protein (TJP2, or ZO-2) as well as AHNAK1, known to be involved in tumor metastasis through EMT." (PMID 35977930, 2022). "The Violin plot showed similar distribution shapes of CTTN in MK5 cells and epithelial tumor cells." (PMID 36523772, 2022). "While Pyk2 regulates invasiveness by controlling cortactin tyrosine phosphorylation-dependent invadopodia maturation and consequent actin polymerization and ECM degradation, FAK controls invasiveness of tumor cells by controlling Src kinase-dependent focal-adhesion mediated motility." (PMID 34440806, 2021). "CTTN overexpression (βadj. = 0.253, P < 0.05), CLDN-1 (βadj. = 0.345, P < 0.01), and CLDN-4 (βadj. = 0.338, P < 0.01) were significantly correlated to the larger tumor dimension in the models adjusted for potential covariates." (PMID 33407452, 2021). "Therefore, this article reviews the correlations between cortactin, the actin cytoskeleton, and the EMT and discusses its clinical value in tumor therapy." (PMID 33195233, 2020). "Tyr421 phosphorylated cortactin was detected in 92% of 64 tumor cores (two of the 66 tissue samples were excluded from further analysis due to low tumor percentage (< 5%); 8% of the cases showed negative tumor cells." (PMID 30976201, 2019). "Additionally, this upregulation of CD44 and CTTN activated the Wnt pathway and further upregulated the expression of CD44, which is a widely accepted marker in stem tumor cells." (PMID 30832692, 2019). "From the GEPIA analysis, the mRNA levels of these factors were slightly downregulated in tumor tissues compared with those in normal tissues, which indicated that posttranslational modification plays crucial roles in CD44 and CTTN expression." (PMID 30832692, 2019).
tumor (continued). "In cryo-conserved PDAC samples of matched non-neoplastic pancreatic and tumor tissue of 11 patients analyzed via qRT-PCR no significant dysregulation of cortactin at the mRNA level was observed." (PMID 30976201, 2019). "As remarkable reduction in the intensities of phosphorylated cortactin and FAK staining was detected in excised tumor specimens from these mice, these results clearly support the notion that tumor-suppressive effect of ISL and THC is associated with their ability to inhibit Src activity." (PMID 30285892, 2018). "There is a positive correlation between CTTN mRNA expression and CRC tumor stage, and CTTN expression is not related to gender, age, or tumor site." (PMID 27903975, 2017). "Cortactin Y421 and Y470, but not Y486, phosphorylation have been shown to be crucial for actin polymerisation in invadopodia and tumour cell invasion." (PMID 27339664, 2016). "In another study, amplification and overexpression of the CTTN gene correlated with lymph node metastasis in ESCC, while in vitro analyses showed a role for Cortactin in anoikis resistance, tumor growth, and lung metastasis of ESCC cells via the PI3K/Akt pathway." (PMID 26345720, 2015). "The result showed that lymph nodes metastasis (P = 0.000), tumor cell differentiation (P = 0.001) and overexpression of CTTN in tumors (P = 0.000) were significant negative prognostic factors for ESCC patients." (PMID 24551190, 2014). "Among those parameters, multivariate analyses using the Cox proportional hazard model revealed that overexpression of CTTN in ESCC tumors (P = 0.001), LN metastasis (P = 0.003) and tumor cell differentiation (P = 0.000) were independent prognostic factors for ESCC, respectively." (PMID 24551190, 2014). "While these studies did not evaluate EGFR degradation, subsequent work in tumor cells with amplified cortactin gene levels indicates that cortactin upregulation prevents EGFR degradation, although the mechanism for this is unclear." (PMID 22952966, 2012). "Stimulation of tumor cells with epidermal growth factor (EGF) leads to phosphorylation of serine residues 405 and 418 within the PR domain, coincident with a characteristic shift in cortactin electrophoretic mobility from 80 kDa to 85 kDa in SDS-PAGE." (PMID 21079800, 2010). "Importantly, we identified a subset of patients with cortactin-overexpressing tumours that displayed low EGFR levels and a survival rate that equalled that of patients with tumoral overexpression of both EGFR and cortactin." (PMID 18268492, 2008). "Interestingly, patients harbouring these tumours displayed a 5-year overall survival rate that was similar to that of patients with tumours that overexpress both EGFR and cortactin (22 vs 19%, respectively)." (PMID 18268492, 2008). "Considering the different functions of cortactin, cyclin D1 and FADD it would be interesting to see whether these genes, coamplified in the same tumour, have a function at specific stages of tumorigenesis." (PMID 18268491, 2008). "By immunohistochemical staining, we could confirm some of these gene products like MTA2, ESAM, and LGALS1 in primary tumour and in metastasized cells in the lung of the two clones, but CTTN only in primary tumour sections not in metastatic cells of the lung." (PMID 34693476, 2022). "Moreover, cortactin is critical for membrane trafficking and promotes the secretion of extracellular matrix (ECM)-degrading proteinases, which are crucial for the invadopodia formation and its function in tumor cell metastasis." (PMID 29152154, 2017). "However, in that same study, Arp2 expression levels in tumor samples correlated with tumor size, depth of invasion, presence of venous invasion, and Cortactin expression but had no prognostic value for patient survival in multivariate analysis." (PMID 26345720, 2015).
tumor (continued). "It is likely that this pathway plays important roles in tumor progression, since elevated expression of ACK1 and cortactin due to gene amplification is found in several tumor types, and dysregulation of ACK1 and cortactin expression alters EGFR internalization dynamics." (PMID 22952966, 2012). "Interestingly, patients with tumours that do not overexpress the EGFR but overexpress cortactin had a 5-year overall survival of 22%, similar to patients with tumours that overexpress both EGFR and cortactin." (PMID 18268492, 2008). "Interestingly, none of the tumour specimens with low cortactin levels (cortactin nonoverexpressors) overexpressed the EGFR." (PMID 18268492, 2008). "However, in our series we identified a group of 29 tumours with intense cortactin expression in which the EGFR was not overexpressed." (PMID 18268492, 2008). "Importantly, cortactin and EGFR expression levels observed in the TMA discs faithfully reflected the staining intensity of these proteins in whole-tissue sections from corresponding tumour blocks in a subset of 30 cases (see Materials and Methods section)." (PMID 18268492, 2008). "This may be the case for the subset of cortactin-overexpressing/EGFR-nonoverexpressing tumours that we describe in which activation or overexpression of signalling components downstream of the receptor could influence cell survival and growth." (PMID 18268492, 2008). "In these tumours, intense cortactin staining occurred in the absence of strong EGFR staining." (PMID 18268492, 2008). "Similarly, CD44 splice isoform switching from CD44v to CD44s was essential for EMT and tumor metastasis, while the interaction of phosphorylated cortactin with CD44s but not CD44v induced the activation of invadopodia driving tumor cell invasion and metastasis." (PMID 40542654, 2025). "It targets several non-histone substrates, including α-tubulin, cortactin, and heat shock protein 90 (HSP90), playing a role in regulating tumor cell proliferation, metastasis, invasion, and mitosis." (PMID 39594707, 2024). "Collectively, these studies demonstrate that cortactin plays a critical role in ROR1-dependent, noncanonical Wnt5a signaling, leading to increased tumor-cell migration and metastasis." (PMID 31667337, 2019). "The fact that the cortactin can still be amplified without cyclin D1 amplification, suggests that EMS1 amplification directly involved in tumor progression." (PMID 29152154, 2017). "While MenaINV is known to increase EGF-elicited phosphorylation of cortactin at tyrosine 42143, whether this increase in cortactin tyrosine 421 phosphorylation occurs within specific subcellular compartments, and how this contributes to tumor cell phenotype, have not been determined." (PMID 27824079, 2016).